EGFR (epidermal growth factor receptor)
Diseases named in the same sentence as EGFR in open-access papers (continued):
Sharing a sentence is not in itself a finding about the gene and the disease.
cancer (continued). "The luminal B subtype carcinomas expressed EGFR (42%, 3/7) and NF-κB (57%, 4/7) more frequently than the luminal A subtype did (17%, 6/35 and 37%, 13/35, respectively)." (PMID 19442295, 2009). "Multiple studies have shown significant crosstalk between α6β4 integrin and EGFR in carcinoma cells." (PMID 19470173, 2009). "Positive EGFR stain was observed in 21% (9/42) of the samples; this staining was more frequently seen in carcinoma of luminal B subtype (42%, 3/7) than in luminal A subtype (17%, 6/35)." (PMID 19442295, 2009). "Increased transforming growth factor-β (TGF-β) expression and epidermal growth factor receptor (EGFR) amplification accompany the emergence of highly aggressive human carcinomas." (PMID 19365582, 2009). "As mTOR signalling is dependent on growth factors, including EGF, we compared everolimus with gefitinib or cetuximab in both wild type and EGFR inhibitor-resistant cancer cell lines, focusing on the mTOR effector p70S6 Kinase." (PMID 18319715, 2008). "Among the PTKs, the EGFR is one of the most widely studied and has emerged as a promising key target for the treatment of cancer." (PMID 18991714, 2008). "The link between HIF-1 and EGF and the reported ability of mTOR inhibitors rapamycin and everolimus to reduce VEGF secretion in vitro and in vivo, renders mTOR inhibitors potentially effective against cancer cells resistant to EGFR inhibitors." (PMID 18319715, 2008). "Epidermal growth factor receptor-targeting agents, with their encouraging efficacy, mild toxicity profile and quality of life benefits, offer hope for patients with advanced cancer." (PMID 18506149, 2008). "In our study we used EGFR and ErbB2 as targets; both are very well characterized in the field of targeted anti cancer therapy." (PMID 18387177, 2008). "ZD1839 (gefitinib, Iressa®), an orally active, selective EGFR-Tyrosine Kinase Inhibitor (TKI) that blocks signal transduction pathways implicated in proliferation and survival of cancer cells and other host-dependent processes that promote cancer growth." (PMID 18435859, 2008). "The central role of the EGFR/ErbB family members in cell migration, proliferation, survival, and transformation identified these transmembrane receptors as targets for cancer therapeutic approaches." (PMID 18702090, 2008). "Molecular inhibition of EGFR/HER1 signaling is extensively investigated as a promising cancer treatment strategy." (PMID 18519000, 2008). "It has been reported that both COX-2 and the epidermal growth factor receptor (EGFR) are activated in most human cancers." (PMID 19055708, 2008). "For example, the Epidermal Growth Factor Receptor (EGFr), a major target for cancer therapy, can be expressed in the transmembrane receptor form or as a soluble isoform that competes with the receptor for binding of ligand." (PMID 18638396, 2008). "In order to evaluate the minimal number of cells for successful EGFR DNA sequence analysis, we compared the quality of DNA chromatograms from exons 18, 19, 20 and 21 of the EGFR gene obtained from 30, 50 and 100 cancer cells." (PMID 18087280, 2008). "As blocking of these processes markedly effects repair of DNA-double strand breaks, this EGFR-coupled radiation response mechanism offers new interventional molecular targets for cancer therapy, especially by radiation therapy." (PMID 18789131, 2008). "The EGFR signalling pathways regulate cell differentiation, proliferation, migration, angiogenesis and apoptosis, all of which become deregulated in cancer cells." (PMID 18958173, 2008). "Targeted therapies usingmonoclonal antibodies against EGFR are highly effective in several human cancer." (PMID 18769552, 2008).
cancer (continued). "EGFR is a major transducer of mitogenic signals involved in cancer pathogenesis and progression upstream of mTOR and an important target for anticancer therapy." (PMID 18319715, 2008). "The potential value of modulating EGFR signaling as a cancer treatment approach is reflected by the broad array of molecular inhibitors that have been developed and launched in clinical trials during recent years." (PMID 18519000, 2008). "Differential sensitivity to EGFR inhibitors have been previously reported for a large panel of cancer cell lines with varying degrees of EGFR expression." (PMID 18177496, 2008). "Strategies to attenuate the activated EGFR in cancers by accelerating the endocytic process have been largely overlooked." (PMID 21892266, 2008). "It should be noted that there are some restrictions to the FDA approved drugs that inhibit EGFR signaling and cancer growth." (PMID 21892266, 2008). "One current strategy to block cancer growth involves the use of antibodies against the extracellular domain of EGFR, which compete with ligand for receptor binding, thereby preventing kinase activation." (PMID 18958173, 2008). "First, despite the wide range of cancers that are characterized by EGFR overexpression and/or hyperactivation, these drugs have only been approved for a limited number of cancers." (PMID 21892266, 2008). "An inhibition of the expression and secretion of VEGF was observed in all cancer cell lines tested, particularly in the EGFR inhibitor-resistant cells." (PMID 18665191, 2008). "Quinazoline tyrosine kinase inhibitors of EGFR have been shown to induce inactive EGFR homodimers and EGFR/HER2 heterodimers in EGFR over-expressing cancer cells as well as decreasing EGFR/HER3 mediated PI3K/Akt pathway." (PMID 18682844, 2008). "The use of radiolabeled anti-EGFR antibodies for EGFR-expressing cancer diagnosis has become the subject of intense investigation as more mAbs with relevant and well-characterized specificities become available." (PMID 18991714, 2008). "PKA has also been proposed as a possible target for cancer therapy, and the therapeutic potential of the combined blockade of EGFR and PKA has been discussed." (PMID 18380891, 2008). "Evidence for a role of HER2 and EGFR in the pathogenesis of various cancers has led to the rational design and development of agents that selectively target HER2 and EGFR." (PMID 18334972, 2008). "In conclusion, the EGFR has been recognized as one of the most promising targets for the treatment of cancer." (PMID 18991714, 2008). "We demonstrated that everolimus is active against EGFR-resistant cancer cell lines and partially restores the ability of EGFR inhibitors to inhibit growth and survival." (PMID 18319715, 2008). "An alternative approach for blocking EGFR function in cancer cells has been the development of small molecules able to interfere with the enzymatic activity of the ligand-activated EGFR." (PMID 18059397, 2008). "The side effects of EGFR tyrosine kinase inhibitors are important challenges in their usage in cancer therapy." (PMID 18519000, 2008). "EGFR, epidermal growth factor receptor, is involved in signaling events in cell proliferation and cancer." (PMID 19079774, 2008). "Epidermal growth factor receptor and other members of this receptor family have already been successful targets for cancer therapy." (PMID 18319714, 2008). "Recently, the efficacy of molecular targeting therapy for various molecules including EGFR/VEGF/HER2 has been proved clinically in a wide range of cancers." (PMID 18087285, 2008). "So far, most of the patients treated with a monoclonal antibodyanti-EGFR Cetuximab (Erbitux, Lyon, France) suffer from colorectal or lung cancers." (PMID 18769552, 2008). "We have shown that enzastaurin alone has an antiproliferative effect on several human cancer cell lines EGFR inhibitor-sensitive and EGFR inhibitor-resistant." (PMID 18665191, 2008).
cancer (continued). "Enzastaurin was evaluated alone and in combination with the EGFR inhibitor gefitinib, on growth and signalling protein expression in human cancer cells sensitive and resistant to anti-EGFR drugs, both in vitro and in nude mice." (PMID 18665191, 2008). "To further investigate the role of everolimus on cancer cells resistant to EGFR inhibitors, we established GEO and GEO-GR xenografts by using BalbC nude mice." (PMID 18319715, 2008). "An important functional difference between TKI and EGFR antibodies lies in the antibodies' ability to attack cancer cells through a combination of mechanisms." (PMID 18702090, 2008). "We used everolimus (RAD001) to inhibit mTOR, alone or in combination with anti-EGFR drugs gefitinib or cetuximab, on human cancer cell lines sensitive and resistant to EGFR inhibitors, both in vitro and in vivo." (PMID 18319715, 2008). "Interestingly, all cases with alterations in EGFR (amplification/mutation) were carcinomas already invading the basal membrane and spreading into the gastric wall (T2-T4), suggesting that alterations of this gene may confer an invasive behaviour to neoplastic cells." (PMID 18199332, 2008). "Identification of appropriate markers that dependably mirror the responses of cancer cells to EGFR-targeted therapy is a clinically important undertaking." (PMID 17931419, 2007). "The constitutive activation of these proteins is seen in a number of different common cancer subtypes, and in particular EGFR and HER2 have become highly pursued targets for anti-cancer drug development." (PMID 17667926, 2007). "As data accumulate, it seems clear that EGFR-mutant “oncogene-addicted” cancers represent a distinct form of NSCLC that can be targeted through novel approaches." (PMID 17973572, 2007). "Experiments have been conducted and shown that p-AKT was up-regulated upon the activation of EGFR and it mediated the signal from EGFR to cancer cell proliferation." (PMID 19662227, 2007). "Another appealing reason is the fact that new approved therapies for those cancers are targeting EGFR, based on the inhibition of its TK activity." (PMID 17453000, 2007). "The activation of EGFR via overexpression of the receptor and/or ligands or its structural alteration, affects a number of processes important to cancer development and progression, including cell proliferation, apoptosis, angiogenesis, and metastasis." (PMID 17956637, 2007). "Epidermal growth factor receptor is a potential target for cancer treatment and new small-molecule tyrosine kinase inhibitor drugs have been designed to inhibit its activity." (PMID 17211472, 2007). "EGFR signalling is critical not only for cell proliferation but also in other processes crucial to cancer progression, and EGFR has therefore been explored as a target for anticancer therapies." (PMID 17311025, 2007). "The epidermal growth factor receptor (EGFR) is frequently overexpressed in many cancers, including non-small cell lung cancer (NSCLC)." (PMID 18154660, 2007). "Searching for novel molecular markers that dependably predict or indicate responses of human cancer cells to epidermal growth factor receptor (EGFR)-targeted therapy is strongly warranted." (PMID 17931419, 2007). "MDA-MB-468 and HCC1937 cells were used as an additional basal-like cancer cell lines as they are triple negative and they overexpress EGFR." (PMID 17875215, 2007). "Gefitinib and other EGFR inhibitors, and results of clinical trials using gefitinib in cancer patients, have recently been reviewed." (PMID 17311025, 2007). "It is also reported that cancer cells having HER2 mutations, present in a very small fraction of NSCLC, are insensitive to EGFR-TKI, but remain sensitive to HER2-targeted therapies." (PMID 17325698, 2007). "Initially the levels of YB-1 and EGFR were compared between 184 htert (immortalized breast epithelial cells) and the cancer cells." (PMID 17875215, 2007).
cancer (continued). "Our findings suggest that NSC-154829, or closely related structures, should be investigated further for treatment of cancers with EGFR pathway activation." (PMID 17437646, 2007). "The evidence implicating EGFR and HER2 in cancer pathogenesis has driven the development of numerous pharmaceutical approaches to treat cancers using drugs that target EGFR or HER2." (PMID 17667926, 2007). "Clinical studies in a number of different cancers known to be driven by EGFR or HER2 show mixed results, and further mechanistic understanding of drug sensitivity and resistance is needed to realise the full potential of this treatment modality." (PMID 17667926, 2007). "Members of the human epidermal growth factor receptor (HER) family have been of considerable interest in the cancer arena due to their potential to induce tumorigenesis when their signalling functions are deregulated." (PMID 17667926, 2007). "Among these targets, the epidermal growth factor receptor (EGFR) has been widely investigated in different human malignancies due to its critical role in cancer proliferation and survival." (PMID 19340316, 2007). "The epidermal growth factor receptor (EGFR) is involved in cancer progression and development and, being overexpressed in a variety of human malignancies, is an attractive target for selective anticancer therapy." (PMID 19340316, 2007). "The principle signalling function of HER3 in cancers appears to be its role as a substrate of EGFR or HER2 and a scaffold for the recruitment of cytosolic signalling proteins." (PMID 17667926, 2007). "Accumulating evidence indicates that the response of cancer cells to EGFR-targeted therapy is a complex process that can be affected by multiple intrinsic and extrinsic resistance mechanisms." (PMID 17931419, 2007). "EGFR is overexpressed or aberrantly activated in different types of human tumors, contributing to the malignant phenotype of cancer cells, and targeted inactivation of EGFR is being intensively explored as a cancer therapeutic approach." (PMID 17877814, 2007). "The epidermal growth factor receptor (EGFR) signaling pathway is an important mediator of cancer cell oncogenesis, proliferation, maintenance, and survival." (PMID 18949068, 2007). "The epidermal growth factor receptor (EGFR) pathways have been investigated as a potential target for cancer therapy because EGFR overexpression is frequently observed and associated with a poor prognosis or resistance to chemotherapy." (PMID 17325698, 2007). "We found that co-culturing DU-145 and PC-3 carcinoma cells with rat hepatocytes resulted in increased E-cadherin expression and decreased EGFR expression." (PMID 17406365, 2007). "The epidermal growth factor receptor (EGFR) lies at the head of a complex signal transduction cascade that contributes to a number of processes important to cancer development and progression." (PMID 16804520, 2006). "Skin toxicity, a common drug-related adverse event observed in cancer patients treated with epidermal growth factor receptor (EGFR)-directed therapies is rarely seen with therapies targeting HER2." (PMID 16306877, 2006). "Diagonal linear discriminant analysis using this gene signature was highly effective in classifying out-of-sample cancer cell lines by sensitivity to EGFR inhibition, and was more accurate than classifying by mutational status alone." (PMID 17096850, 2006). "This supports the case for investigating the potential clinical role of HER2 overexpression as a predictive marker for response to anti-EGFR therapy in human cancers." (PMID 16622439, 2006). "At this point, it has to be reminded that cancer cells rely on several, sometimes, redundant activation pathways; EGFR is only one of them." (PMID 16722544, 2006). "Epidermal growth factor receptor is overexpressed in many different cancer types, including 60–80% of colon cancers, which correlates with a poor prognosis." (PMID 16570047, 2006).
cancer (continued). "The EGFR signalling pathway regulates cell differentiation, proliferation, migration, angiogenesis, and apoptosis, all of which become deregulated in cancer cells." (PMID 16508634, 2006). "The activity of specific monoclonal antibodies on apparently normal colorectal mucosa overexpressing EGFr, and the crosstalking of different biological pathways leading to cancer growth should be topics for preclinical research." (PMID 17088913, 2006). "There is a large body of scientific evidence that the epidermal growth factor receptor (EGFR) pathway contributes to a number of processes involved in cancer cell proliferation, survival and invasion rendering it an attractive target for anticancer therapy." (PMID 16685276, 2006). "Despite with relatively small cohorts, these studies provided rationales for future extensive research that examines the prognostic value of EGFR in larger population with various cancer types." (PMID 16434982, 2006). "The role of EGFR as an oncogene has been elucidated for many years and the level of EGFR protein expression has been shown to be elevated in multiple cancer types relative to normal tissues." (PMID 16911776, 2006). "A Pinpoint Slide DNA Isolation System was used to extract DNA from cancer cells alone on glass slides, and the EGFR gene status was analysed using LH-MSA as described in the Patients and methods." (PMID 17047654, 2006). "Cancer cell chemotaxis downstream of the epidermal growth factor receptor (EGFR) pathway, involves the activation of cofilin by phospholipase Cγ (PLCγ)." (PMID 16756685, 2006). "Given the biological importance of the EGFR molecular network in carcinomas, several molecules that can inhibit the EGFR tyrosine kinase domain have been synthesised." (PMID 17047654, 2006). "Epidermal growth factor receptor signalling in the maintenance of carcinomas during intestinal tumorigenesis has been found in animal experiments." (PMID 17088913, 2006). "As EGFR is also a potential therapeutic target, evaluation of EGFR overexpression is paramount in cancer strategy." (PMID 15986037, 2005). "This EGFR-transmitted proliferation effect of the cancer cell line was completely inhibited by gefitinib, an EGFR tyrosine kinase inhibitor." (PMID 15785737, 2005). "Manipulation of growth factor receptors such as EGFR and the subsequent effect on downstream signalling cascades has been of much interest in the development of novel cancer therapies." (PMID 15611794, 2005). "For example, the treatment of cancer cells with EGFR tyrosine kinase inhibitor markedly potentiates the efficacy of many cytotoxic agents against several human cancer xenografts." (PMID 15655552, 2005). "Among the recent advances in the molecular targeted therapy of cancer, the applications focused on epidermal growth factor receptor (EGFR) are currently the most promising and the most advanced at clinical level." (PMID 15756277, 2005). "The mechanism of action on cancer cells of EGFR blockers such as AG 1478, mAb225, and gefitinib is generally cytostatic and proceeds via a G0/G1 arrest." (PMID 15987464, 2005). "Inhibitors of EGFR activation via antibodies to the extracellular protein or via tyrosine kinase inhibitory molecules provide promising new approaches to both cancer treatment and prevention." (PMID 16160697, 2005). "The epidermal growth factor receptor (EGFR) is a cell membrane receptor that plays a key role in cancer development and progression." (PMID 15785737, 2005). "Aberrant signalling occurring from EGFR results in its conversion into an oncoprotein, and the consequent malfunction of cellular signalling networks leads to the development of cancers and other proliferative diseases." (PMID 16202132, 2005). "Growth and metastasis of cancer require several processes; angiogenesis plays a key role, and it is well known that EGFR signalling pathways have an important role in the regulation of angiogenesis." (PMID 15785737, 2005).